GATA2 (GATA binding protein 2)
Diseases named in the same sentence as GATA2 in open-access papers (continued):
Sharing a sentence is not in itself a finding about the gene and the disease.
tumor (continued). "Immunohistochemical studies revealed diffuse co-secretion of both TRH and TSH by the tumor, with diffuse expression of lineage-restricted transcription factors (ie, Pit-1 and GATA-2), which may have resulted in a continuous autocrine/paracrine regulation of TSH secretion." (PMID 32706866, 2020). "Tumor specimens exhibited elevated expression of DTX2, SALL1, ZNF93, ZNF146 and ZSCAN16, contrasting with reduced levels of EGR2, GATA2, and ZEB2." (PMID 40647501, 2025). "GATA2 IHC and scoring was performed similarly to the UW1 cohort, except whole slides of tumor were stained and scored." (PMID 40168074, 2025). "In ccRCC, NFIC and GATA2 regulate ALDH6A1 expression, enhancing its capacity to manage oxidative stress and detoxify harmful metabolites, which is crucial in the tumor environment." (PMID 39348357, 2024). "More importantly, cluster 2 exhibits a strong positive correlation with transcription factors WNT5A, WNT10A, GATA2, and FOSL2, all recognized for their involvement in tumor stemness." (PMID 38339238, 2024). "In the present study, we first reported low expression of GATA2 in the majority of B-ALL patients, which was consistent with the origination of this tumor from the early developmental stage of B lymphoid." (PMID 35087776, 2021). "HDC, GATA2, SLC45A3, and NTRK1 were downregulated in tumor-bearing mice subjected to chronic unpredictable mild stress (CUMS)." (PMID 34650925, 2021). "Through a systems medicine approach, it was determined that hub biomolecules, AR, GATA2, miR-124, TOR1AIP1, ESR1, EGFR, STAT1, miR-192, GATA3, COL1A1, in tumor microenvironment generic network." (PMID 33907495, 2021). "Meanwhile, we were able to identify another MLL B-ALL case, SJALL043839_D1, with aberrant GATA2 transcription from a previously published ALL cohort, in which both RNA-seq and whole-genome sequencing (WGS) data were available for tumor cells." (PMID 35087776, 2021). "The tumor was positive for thyrotropin (TSH), TSH-releasing hormone (TRH), Pit-1, GATA-2, and most neuronal markers." (PMID 32706866, 2020). "Otherwise, PDS increased the proportion of both hematopoietic stem cells and erythroid progenitor cells in the bone marrow, but inhibited spleen erythroid differentiation via inhibiting secretion of tumor EPO, GATA-1, and GATA-2." (PMID 32015754, 2020). "We further determined the expression of Bmi1, MICA/B, GATA2 and p-AMPK in the tumor tissues of different treatment group." (PMID 31088566, 2019). "The tumor suppressor function of GATA3 is in agreement with the observation that, as shown by the H&E staining, the AP and DLP of GATA2/3 double KO mice resembled PIN III to PIN IV lesions with tufting and micro-papillary patterns." (PMID 27374105, 2016). "Decreased expression of intratumoral GATA2 protein significantly correlated with pivotal clinicopathologic factors related to HCC invasiveness and independently predicted elevated risks of tumor recurrence and patient death." (PMID 24498120, 2014). "For the genes WT1, GATA2, and FGFR3, the expression pattern in surgically dissected tumor tissue was consistent with that in the microdissected epithelial cells." (PMID 20426842, 2010). "Scoring at UMN was performed blindly by a senior UMN gynecologic pathologist and a pathology resident who were asked to score the percent GATA2+ tumor nuclei without any additional training." (PMID 40168074, 2025). "Similarly, SLC12A1 is regulated by NFIC, GATA2 and FOXC1, ensures ionic balance and cellular volume, thereby supporting tumor cell survival and aggressive behavior." (PMID 39348357, 2024).
tumor (continued). "The results indicated that the expression of GATA1, GATA4 and GATA6 remarkably varied across the tumor stages, whereas GATA2, GATA3 and GATA5 demonstrated no significantly changes in different tumor stages." (PMID 34093794, 2021). "Further immunohistochemical studies for these transcription factors revealed diffuse and strong nuclear immunoreactivity for Pit-1 and GATA-2, but not for SF-1, Tpit, and ER, confirming thyrotropic cell differentiation of tumor cells." (PMID 32706866, 2020). "Furthermore, we identified the novel role of transcription factors GATA-2 and GATA-3 in suppressing MICA/B expression, which contributes to tumor escape from NK lysis." (PMID 27528231, 2016). "Our results provided GATA2 SNP rs2335052 as a prognostic factor independent of tumor stages, and raise the possibility to identify patients with higher risk of recurrence and should be treated with adjuvant chemotherapy." (PMID 26287967, 2015). "GATA-2 showed significantly higher expression values in MYCN-nonamplified compared with MYCN-amplified tumours (P<0.001)." (PMID 19707195, 2009). "As expected, HPAF-II xenografts showed glandular structures, typical of highly differentiated tumors, with higher FOXA1 expression, whereas PANC-1 xenografts exhibited solid and compact tumor sheets without lumens, indicative of poor differentiation, along with higher GATA2 and ABCC4 expression." (PMID 39114357, 2024). "Tumor cellular assays, qRT-PCR, western blot, ChIP, luciferase assays and CRISPR-Cas9 editing methods were performed to mechanistically understand the cooperation of GATA2 with SMAD4 in promoting TGFβ1 and AR signaling and mediating inherited PCa risk and progression." (PMID 37550764, 2023). "However, a positive correlation between GATA2 and MDM2 expression in tumor tissues was observed." (PMID 34592889, 2021). "In addition, significantly higher expression values were also found for GATA-2 in tumours without MYCN-amplification and stage 4S tumours (vs stage 4)." (PMID 19707195, 2009). "However, as we found that SIN3B protein levels measured by IHC did not clearly correlate with GATA2 across a larger USC tumor cohort, it is likely that clinically relevant GATA2 regulation of SIN3B may not extend across the full USC tumor spectrum." (PMID 40168074, 2025). "Interestingly, none of these variants were in GATA2, although in 14 primary MDS cases with tumor-only material available there were 3 additional GATA2 variants (1 case with 2 separate mutations) with VAF’s > 40% suggesting that they may be germline events." (PMID 29146900, 2017). "Although GATA2 itself is not druggable, the combined proteasome and Rho signaling inhibition resulted in a robust suppression of KRAS-mutant tumor growth." (PMID 30060526, 2018). "To examine whether the CGA/EGFR/GATA2 circuit occurs in GC patients, we stained for GATA2 and p-EGFR in 31 paired tumor specimens from patients who did not respond to chemotherapy." (PMID 35289315, 2022). "The results showed that the expression of SH2D2A and GATA2 were upregulated (P = .0067 and P = .6021, respectively), while CXCL8, LIF, and VASH2 were downregulated in IVL tumor samples compared to nontumor tissue (P = .9281, P = .5406 and P = .0625, respectively)." (PMID 32372565, 2020). "Similarly, analysis of FOG-2, GATA-2 and GATA-3 expression by real-time RT-PCR disclosed only lower FOG-2 levels in MYCN-amplified vs MYCN-nonamplified tumours at a significant level." (PMID 19707195, 2009).
infection (32 papers, 2009 to 2025). The state of being infected such as from the introduction of a foreign agent such as serum, vaccine, antigenic substance or organism. "We present the case of a young adult man with severe lung alveolar proteinosis, granulomatous disease, infections, and autoimmune complications present before we confirm GATA2 as a newly described mutation." (PMID 41322420, 2025). "GATA2 is involved in familial leukemia and in a complex congenital immunodeficiency that evolves over decades and leads to predisposition to infection and myeloid malignancy." (PMID 40725177, 2025). "In two cases from our center, GATA2 deficiency-associated infections were likely to be the occult cause of HLH." (PMID 37680631, 2023). "Although it was not mentioned in other previous case reports, erythema nodosa appeared in two HLH patients with GATA2 deficiency identified as different infections in our center." (PMID 37680631, 2023). "Although optimum timing and indication of HSCT in GATA2 deficiency is still unclear, frequent/severe infection and serious organ damage, such as pulmonary function, can be a trigger for launching HSCT." (PMID 36185231, 2022). "Although the results are encouraging, only four patients were under the age of 20 years, and infection was the indication in approximately half of the patients, rendering it difficult to interpret the results for pediatric GATA2-deficient patients with MDS." (PMID 34244664, 2021). "Allogeneic HSCT is the only curative therapy for hematological complications of GATA2 deficiency, and has been shown to eradicate clonal malignancy, restore normal hematopoiesis, clear underlying infections and improve pulmonary function." (PMID 34244664, 2021). "It has been observed from analyzing the association between phenotype and the type of GATA2 mutation that severe infections are more frequent and have an earlier onset in patients with null mutations." (PMID 33066218, 2020). "Perhaps one of the most striking features of some patients with GATA2 mutation is how little infection they experience despite very profound cellular deficiencies." (PMID 25707267, 2015). "Patients with familial MDS/AML associated with GATA2 mutation have increased risks for severe infections, particular intracellular organisms." (PMID 26445707, 2015). "AML with GATA2 mutation usually have a poor outcome due to comorbidities such as propensity of infections." (PMID 26445707, 2015). "A recent study reported six patients who underwent allogeneic stem cell transplant for GATA2 deficiency had excellent outcomes except one who died from infection." (PMID 24754962, 2014). "Here, we describe that GATA2 mutations in immunocompromised individuals enhanced their susceptibility to Mh, which could manifest in an infection of the skin and CNS." (PMID 40762982, 2025). "The specific mutation in GATA2 identified in all 4 Mh-infected cases in the coding third exon (p.A164T, rs2335052) has been linked to M. kansasii and M. fortuitum and infection recently reported in patients with Mh infection, but it was classified as “benign” (nondisease causing)." (PMID 40762982, 2025). "GATA2 deficiency has highly variable penetrance, and infections or other factors may affect epigenetic mechanisms to trigger pathogenesis and alter penetrance." (PMID 37680631, 2023). "However, reduced intensity conditioning is preferred in patients with GATA2 deficiency due to comorbidities such as concomitant infections and PAP." (PMID 36185231, 2022). "Reduced toxicity conditioning approaches may be of particular interest in patients who have MDS due to underlying inherited marrow failure syndromes such as GATA2 deficiency that increase the risk for infection, or patients with treatment-associated MDS and a history of prior intensive chemotherapy." (PMID 40427141, 2025).
infection (continued). "In this study, the AAV9 vector was employed to mediate the expression of GATA2, primarily based on its stability in the dental pulp microenvironment and its efficient infection of SCAPs (stem cells from the apical papilla)." (PMID 40243520, 2025). "The molecularly defined IEI associated with severe or disseminated cryptococcosis strikingly overlap with those that predispose one to infection with TDEF, namely, MSMD, GATA2, CD40L deficiency, STAT1 GOF, and DN-STAT3; these IEI have been detailed above." (PMID 36986378, 2023). "Ad.Cre infection led to reduced GATA2 levels in endothelial cells, and cardiomyocytes plated on top of these cells were more hypertrophied compared to those plated on Ad.Control-infected endothelial cells." (PMID 36552246, 2022). "Genes regulated by GATA1 and GATA2 were downregulated during acute infection, but upregulated whenever appropriate erythropoietic output was restored." (PMID 28938907, 2017). "The target genes of GATA1 and GATA2 correlated with the small but significant decrease (p = 0.045) in the frequency of the erythroid progenitor population in the BM during acute infection." (PMID 28938907, 2017). "Furthermore, AAV9 demonstrates robust tissue penetrability, enabling efficient infection of diverse cell types within the pulp chamber, such as DPSCs and odontoblasts, thereby effectively modulating GATA2 expression and promoting dentin regeneration." (PMID 40243520, 2025). "Our findings revealed that the levels of Gata2, Fat4 and Pkd1, which are related to cell polarization, as well as Egfl7, Nrp1 and Foxc2, which are related to valve development, were downregulated after infection." (PMID 38638427, 2024). "For children with GATA2 mutations and MDS, the ideal time for HSCT seems to be during the hypo cellular phase of the disease and before serious complications (i.e., invasive infections) or progression to advanced MDS occur." (PMID 33066218, 2020). "First, the expression of GATA1 and GATA2 was examined directly to understand if the gene expression of these proteins was changed during infection, which could directly impact the erythropoietic response during infection." (PMID 28938907, 2017). "Infections with other disseminated pathogens are frequently observed in GATA2-deficient patients, including non-tuberculous mycobacteria, herpes viruses (varicella zoster virus, Epstein–Barr virus, and cytomegalovirus), and invasive fungal and yeast infections." (PMID 41322420, 2025). "As we know, erythema nodosa may indicate an underlying infection with non-tuberculous mycobacteria or fungi in GATA2 deficiency, but the patient’s nodule biopsy did not reveal evidence of infection." (PMID 37680631, 2023). "In essence, the low levels of GATA-2 in more differentiated cell types that HCMV lytically infects may result in the additional requirement of IE72 activity against hDaxx:ATRX to promote LUNA gene expression during lytic infection." (PMID 23736881, 2013). "Hepatitis B virus (HBV) releases HBc and HBx proteins to promote the expression of transcription factors GATA-2 and GATA-3 after infection, and GATA-2 and GATA-3 specifically inhibit MICA/B expression by directly binding to the promoter region of MICA/B." (PMID 30813924, 2019). "Importantly, in 70% of our patients, severe infection, including HPV, was the initial presentation of GATA2 haploinsufficiency." (PMID 39267745, 2024). "Despite the observation that the loss of B-cells is a common feature of GATA2 deficiency, children with GATA2 germline mutations often present as MDS without prior infections." (PMID 34244664, 2021). "We found that inhibitors of AKT, mTOR, and PI3K completely abolished the expression of NF-E2 and GATA2 with or without infection, suggesting that these proteins had a significant role as regulatory molecules of megakaryopoiesis process." (PMID 34513730, 2021).
infection (continued). "It has been documented that alloHSCT may be a modality of a cure for GATA2 deficiency-related HLH, regardless of the presence of active infection." (PMID 37680631, 2023). "Next, the genes regulated by GATA1 and GATA2 were examined to identify whether the genes regulated by these proteins were differentially regulated even though transcription of GATA1/GATA2 was not altered significantly during acute infection." (PMID 28938907, 2017). "GATA2 gene expression did not change throughout the initial infection." (PMID 28938907, 2017). "In the bone marrow, the mRNA expression of erythroid differentiation genes (α-globin, β-globin, ALAS2) were inhibited by 50%, but mRNA levels of erythroid receptor (c-kit, EpoR) and transcription factors (GATA1, GATA2, FOG1) were not affected by the infection." (PMID 23533629, 2013).
hematological malignancies (28 papers, 2011 to 2025). "GATA2 deficiency is a rare genetic disorder affecting hematopoiesis, immune function, and the lymphatic system, predisposing individuals to infections and hematologic malignancies." (PMID 41438140, 2025). "GATA2 deficiency is an autosomal dominant disorder with various manifestations including hematologic disease and inborn errors of immunity." (PMID 40264496, 2025). "The p.Arg396Trp mutation in the GATA2 gene is a significant variant linked to multiple hematological disorders, especially those characterized by haploinsufficiency." (PMID 41154393, 2025). "Of note, GATA2 is a central regulator of hematopoietic stem and progenitor cell function and a causal factor in several blood disorders." (PMID 41318785, 2025). "GATA2 defects lead to hematological malignancies in 70 % of patients by age 50 with a lifetime risk of AML and MDS of 32 % and 21 % respectively." (PMID 40535318, 2025). "As a vital TF in multilineage hematopoiesis, mutations in GATA2 induce several hematological diseases." (PMID 37662030, 2023). "Recent advances in clinical research have led to an emerging theory that the GATA2 gene is causative for congenital hematopoietic diseases in autosomal dominant traits, including Emberger syndrome, DCML deficiency, and MonoMAC syndrome." (PMID 35440757, 2022). "For example, studies in kindreds with GATA2 deficiency have reported that by age 40 years, 80% of affected individuals presented with either hematologic malignancies or infections." (PMID 35356204, 2022). "For example, in a single center cohort of patients undergoing SCT for GATA2 deficiency-related blood disorders, we found an increased risk of thrombotic and neurological complications, compared to patients with GATA2 wild-type MDS or ALL." (PMID 35356204, 2022). "Taking into account that more than 80% of patients with GATA2 deficiency present with a hematologic malignancy around the age of 40 years, HSCT is generally considered early in the clinical course." (PMID 35273927, 2022). "The present mouse model provides an avenue for the understanding of molecular mechanisms underlying the pathogenesis of GATA2-related hematopoietic diseases." (PMID 35440757, 2022). "In Norway, exome-based panels including GATA2 are offered as a routine diagnostic laboratory service for constitutional hematological disorders and PID." (PMID 34893945, 2022). "Previous reports have suggested that plasma levels of FLT3LG can be used as predictor of hematological disease in GATA2 deficiency, and used in clinical monitoring post-HSCT." (PMID 34893945, 2022). "In this study, we created five human GATA2 mutants that were reported to be associated with hematological disorders." (PMID 34576178, 2021). "Recent studies revealed that loss-of-function mutations in GATA2 are associated with hematological disorders." (PMID 34576178, 2021). "Missense mutations within the N-terminal zinc-finger domain (ZF1) or the C-terminal domain were also reported in patients with GATA2 haploinsufficiency associated with hematological disorders." (PMID 34576178, 2021). "There is growing evidence that altered GATA2 expression and constitutive heterozygous GATA2 mutation are associated with hematologic malignancies, as well as the development and progression of various solid tumors." (PMID 26287967, 2015). "This study shows that GATA2 mutations in patients with hematologic diseases and severe PAP occur at a relatively low frequency." (PMID 26264606, 2015). "Here, we investigate a cohort of children and adults with severe and chronic PAP and hematologic disease for the presence of GATA2 mutations." (PMID 26264606, 2015). "Clinically, GATA2 mutations are associated with various hematological malignancies." (PMID 41154393, 2025).